ADIPOR1 (adiponectin receptor 1)
Diseases named in the same sentence as ADIPOR1 in open-access papers (continued):
Sharing a sentence is not in itself a finding about the gene and the disease.
prostate carcinoma (4 papers, 2012 to 2017). A carcinoma that arises from epithelial cells of the prostate gland. "On the contrary, LEPR rs1137101 (allele contrast: OR 0.843, 95%CI 0.730-0.973) and ADIPOR1 rs2232853 (allele contrast: OR 0.638, 95%CI 0.535-0.760) variants were associated with decreased risk of prostate cancer." (PMID 27768592, 2016). "In the meta-analysis, LEP rs7799039 (allele contrast: OR 1.133, 95%CI 1.024-1.254), ADIPOQ rs2241766 (allele contrast: OR 1.201, 95%CI 1.015-1.422) and ADIPOR1 rs10920531 (allele contrast: OR 1.184, 95%CI 1.075-1.305) variants were identified to be correlated with increased risk of prostate cancer." (PMID 27768592, 2016).
renal cell carcinoma (4 papers, 2014 to 2024). "Regarding to renal cell carcinoma (RCC), the ratio of TXNDC5/AdipoR1 expression was significantly higher in metastatic renal cell carcinoma tissues than in nonmetastatic controls." (PMID 38629066, 2024). "Adiponectin, via AdipoR1, inhibits mTOR through AMPK activation in renal cell carcinoma (RCC), suppresses vascular endothelial growth factor (VEGF), MMP-2 and MMP-9 and increases TIMP-1 and TIMP-2 secretion, resulting in decreased growth, dissemination and angiogenesis of RCC." (PMID 37686525, 2023).
cardiac hypertrophy (3 papers, 2013 to 2016). "To determine which receptor was responsible for the effect of APN on miR-133a in Ang II induced cardiac hypertrophy, we firstly detected AdipoR1 and AdipoR2 mRNA expression in NRVMs stimulated with Ang II." (PMID 26845040, 2016). "The prevention effect of losartan on the AngII-reduced AdipoR1 expression will provide further understanding of the pathogenesis of cardiac hypertrophy and provide novel insights into this anti-remodeling therapy." (PMID 23349663, 2013). "Considered together, our results suggest that the reduced AdipoR1 expression by AngII may contribute to the attenuated adiponectin signaling, thereby reducing the protective effect of adiponectin and resulting in abnormal metabolic change and cardiac hypertrophy." (PMID 23349663, 2013). "However, angiotensin II-infusion done on normal rats induced cardiac hypertrophy and reduced the expression of AdipoR1 but not AdipoR2." (PMID 27092079, 2016).
Cognitive impairment (3 papers, 2019 to 2025). Abnormal cognition is characterized by deficits in thinking, reasoning, or remembering. "In the context of sepsis-associated encephalopathy (SAE), a severe neurological complication of sepsis, the downregulation of adiponectin receptor 1 (AdipoR1) in the hippocampus is linked to cognitive impairment, synaptic damage, and neuronal loss." (PMID 40652274, 2025). "In summary, our study supports the notion that the chronic consumption of HFD induces cognitive impairments through the adipoR1/AMPK/IRS1 axis, leading to the development of AD-like pathology." (PMID 31963819, 2020).
fibrosis (3 papers, 2015 to 2023). the formation of excess fibrous connective tissue in an organ or tissue in a reparative or reactive process. "Knockdown of AdipoR1 using siRNA reversed the APN-mediated protective effect against paraquat-mediated fibrosis, demonstrating the importance of the APN-AdipoR1 pathway in fibroblasts for protection against pulmonary fibrosis." (PMID 37724101, 2023).
liver cancer (3 papers, 2022 to 2025). An epithelial or non-epithelial malignant neoplasm that arises from the liver. "Our earlier research has found that AdipoR1 plays a pivotal role in modulating radiosensitivity among liver cancer patients undergoing stereotactic body radiotherapy (SBRT)." (PMID 39849382, 2025). "Our previous study revealed that Adiponectin Receptor 1 (AdipoR1) is involved in regulating radiation resistance in liver cancer patients treated with stereotactic body radiotherapy." (PMID 39849382, 2025). "In our previous work, we found that AdipoR1 is a prognostic biomarker for HCC after SBRT in primary liver cancer and blocking AdipoR1 enhances radiation sensitivity in hepatoma carcinoma cells both in vitro and in vivo." (PMID 35733794, 2022). "Our previous findings highlighted the role of AdipoR1 in liver cancer, proving that AdipoR1 was highly expressed in liver cancer and that knockdown of AdipoR1 could promote cell death, which is also consistent with the results of this study." (PMID 39849382, 2025).
lung fibrosis (3 papers, 2015 to 2023). "Taken together, AdipoR1 signaling in lung fibroblast may modify the formation of lung fibrosis in models of injury." (PMID 32889775, 2020). "To test our hypothesis APN influences pulmonary fibrosis directly via lung fibroblasts, we confirmed the presence of AdipoR1 and AdipoR2 (the two known transmembrane APN receptors) in human lung fibroblasts WI-38 via Western and RT-PCR." (PMID 25945502, 2015). "AdipoR1/R2 is expressed on lung fibroblasts and rAPN via binding to AdipoR1 blocked TGF‐β and lung fibrosis." (PMID 32889775, 2020). "Thirdly, we demonstrate lung fibroblasts express functional AdipoR1, supporting the potential utilization of APN as an agent mitigating lung fibrosis." (PMID 25945502, 2015). "Functional AdipoR1 are expressed by human WI-38 lung fibroblasts, suggesting potential future clinical applicability of APN against pulmonary fibrosis." (PMID 25945502, 2015).
lymph node metastasis (3 papers, 2016 to 2025). "Moreover, a positive correlation between the tumor size and adiponectin receptor 1 (AdipoR1) expression has been registered in the early stages of CRC cases, while its overexpression is also associated with lymph node metastasis and poor prognosis." (PMID 37760840, 2023). "Moreover, recent investigations have shown reduced AdipoR1 expression in tumors with lymph node metastasis and venous invasion." (PMID 26931562, 2016).
morbid obesity (3 papers, 2020 to 2023). An excess of body weight, normally defined as an individual with a body mass index greater than 35 or a body weight greater than one hundred percent of ideal body weight. "We observed a positive AdipoR1 immunoexpression for adipocytes from the control group and a reduced, even negative AdipoR1 immunoexpression for the adipocytes from the group with morbid obesity." (PMID 37109222, 2023). "When extensive weight gain occurs, as in the model of morbid obesity (26 weeks), we found an increase in AdipoR1." (PMID 33256137, 2020). "The gene expression of ADIPOR1 seemed to be slightly, but non-significantly, upregulated in the peripheral blood immune cells of patients with morbid obesity compared to the CTRL but reached CTRL levels at 3 – 5 months p.s.." (PMID 37266430, 2023). "An important finding was the negative adipoR1 and adipoR2 immunoexpression in PVAT adipocytes of patients with morbid obesity." (PMID 37109222, 2023).
pancreatic cancer (3 papers, 2014 to 2018). "The results showed that all the examined cell lines preferentially expressed AdipoR1, and pancreatic cancer cell lines showed a higher level of AdipoR1 than normal epithelial HPAEpiC cells." (PMID 30038429, 2018). "Expression levels of AdipoR1 and AdipoR2 were also decreased in murine pancreatic cancer samples and in cell lines Panc02, P-4313, and K-8484 when compared to normal murine pancreatic tissue." (PMID 29156726, 2017). "We further characterized the mRNA expression of AdipoR1 and AdipoR2 in human and murine pancreatic tumor tissue as well as PDAC cell lines relative to normal pancreas utilizing quantitative PCR analysis." (PMID 29156726, 2017). "To determine the role of AdipoR in pancreatic cancer growth, we first tested the expression of AdipoRs using RT-PCR in H7 and Panc02 cell lines and found that both cell lines expressed AdipoR1 and AdipoR2." (PMID 25051362, 2014). "Adiponectin has two receptors, AdipoR1 and AdipoR2, both of which are highly expressed in tumor tissues of pancreatic cancer." (PMID 25051362, 2014). "Knockdown of AdipoR1 in H7 and Panc02 cells significantly reduced tumor size and tumor weight, suggesting that AdipoR1 was more important for adiponectin promotion of pancreatic cancer growth." (PMID 25051362, 2014). "Further experiments showed that adiponectin inhibited the apoptosis of pancreatic cancer cells via AdipoR1, which was consistent with the effect on myocytes." (PMID 25051362, 2014). "In addition, AdipoR1 knockdown markedly decreased the expression of Ki-67, which indicated that AdipoR1 was indispensable for adiponectin-induced proliferation of pancreatic cancer cells." (PMID 25051362, 2014). "We found that adiponectin significantly inhibited the apoptosis of both human and mouse pancreatic cancer cells via adipoR1, but not adipoR2." (PMID 25051362, 2014).
polycystic ovaries (3 papers, 2013 to 2023). "A significantly lower proportion of theca cells expressed adiponectin receptors 1 and 2 (AdipoR1, AdipoR2) in polycystic ovaries than in normal ovaries." (PMID 24260388, 2013). "For AdipoR1, the proportion of positively stained TCs, mean (95% of confidence interval - CI) was 0.29 (0.20, 0.38) in polycystic ovaries versus 0.52 (0.32, 0.72) in normal ovaries (p = 0.002, Mann-Whitney test)." (PMID 24260388, 2013). "In addition to lower levels of adiponectin, there is a decrease in ADIPOR1 and ADIPOR2 receptors in the theca of polycystic ovaries compared to normal ovaries." (PMID 27158926, 2016).
retinitis pigmentosa (3 papers, 2018 to 2019). Retinitis pigmentosa (RP) is an inherited retinal dystrophy leading to progressive loss of the photoreceptors and retinal pigment epithelium and resulting in blindness usually after several decades. "A gene mutation in ADIPOR1 causes human retinitis pigmentosa (with photoreceptor loss resulting in blindness)." (PMID 29180355, 2018). "Taken together, the enrichment of ADIPOR1 in the retina combined with its retinitis pigmentosa causing mutations, described ceramidase activity, and dysregulation of IRBP, appears to point toward a pivotal role in the visual cycle that requires further exploration." (PMID 30254279, 2018). "Importantly, much like the recent ADIPOR1 reports, MFRP mutations are also known to cause retinitis pigmentosa in human patients and it will be instrumental to assess whether their disease is caused by ADIPOR1 loss and whether it can be prevented via rescue of ADIPOR1 expression." (PMID 30254279, 2018).
sarcopenia (3 papers, 2020 to 2025). Progressive decline in muscle mass due to aging which results in decreased functional capacity of muscles. "AdipoRon treatment effectively corrected all the abnormalities associated with sarcopenia, mainly via the AdipoR1-AMPK axis." (PMID 39334732, 2024). "Our findings demonstrate that three months of oral AdipoRon treatment in aged male C57/BL6J mice rescues all sarcopenia-related abnormalities and inflammaging, primarily through the AdipoR1-AMPK axis." (PMID 39334732, 2024). "Aging‐related decreased levels of AdipoR1 in skeletal muscle might contribute to sarcopenia with impaired muscle function and metabolic defects." (PMID 39764565, 2025). "Previous studies also demonstrated that ADPN and AdipoR1 regulate the expression and activation of PPARγcoactivator-1α [PCG-1α], a key component of sarcopenia, by Ca2+ signalling, AMP-activated protein kinase (AMPK), and SIRT1." (PMID 32612097, 2020).
thyroid cancer (3 papers, 2021 to 2024). "AdipoR1 and AdipoR2 were expressed in normal thyroid cells, Nthy-oris-3 (N9), and thyroid cancer cells, TPC-1, K-1, KTC-1 and BCPAP." (PMID 39349421, 2024). "In this study, we identified adiponectin receptor 1 (AdipoR1) and AdipoR2 on the surface of thyroid cancer cell lines." (PMID 39349421, 2024). "In cell function experiments, AdipoRon, a small molecule agonist of AdipoR1 and AdipoR2, inhibited proliferation, clone formation, migration, and invasion in thyroid cancer cells, and induced differentiation in thyroid cancer cells." (PMID 39349421, 2024). "q-RT-PCR showed that the vast majority of the thyroid cancer cell lines tested, although with heterogeneity, expressed leptin and Acrp30 (AdipoR1, AdipoR2, and T-Cadherin) receptors when compared to Nthy-ori 3-1." (PMID 33587254, 2021). "We identified AdipoR1 and AdipoR2 on the surface of thyroid cancer cells." (PMID 39349421, 2024). "Immunofluorescence staining showed AdipoR1 and AdipoR2 on the surface of thyroid cancer cells." (PMID 39349421, 2024). "Further immunohistochemical staining results showed that AdipoR1 and AdipoR2 expression is barely detectable in tumor-adjacent normal thyroid tissue; however, AdipoR1 expression is found in 27% of thyroid cancer tissues, and AdipoR2 expression is found in 47% of such tissues." (PMID 33815885, 2021).
type 1 diabetes (3 papers, 2019 to 2025). "In both type 2 and type 1 diabetes models, knockdown of AdipoR1 nearly abrogated the pro-repair effect of ADPN on corneal epithelial injury, whereas AdipoR2 silencing had no such impact, indicating that ADPN promotes corneal epithelial repair specifically through AdipoR1." (PMID 41146365, 2025). "Autoantibodies against AdipoR1 CTF344–375 have been recently shown to develop during the onset of type 1 diabetes in the non-obese diabetic mouse model and correlated with loss of AdipoR1 signaling of AMBK in the pancreas." (PMID 33511378, 2020).
adenoma (2 papers, 2011 to 2014). A neoplasm arising from the epithelium. "AdipoR1 and AdipoR2 mRNA expression levels were significantly lower in the advanced adenoma and CRC groups than those in the controls." (PMID 25370174, 2014). "We examined AdipoR1 and AdipoR2 mRNA and protein expression levels in specimens from control, advanced adenoma, and CRC tissues by qRT-PCR and immunohistochemical staining." (PMID 25370174, 2014). "AdipoR1 and AdipoR2 expression by immunohistochemical staining were localized in the colon epithelium and was positive in all (100%) of the control and advanced adenoma tissues and in 62.8% and 88.5% of CRC tissues." (PMID 25370174, 2014).
Arthritis (2 papers, 2020 to 2021). Inflammation of a joint. "Together, our data suggest that AdipoR1 knockout ameliorates arthritis symptoms in AIA mice, and is accompanied by decreased IL-17 expression." (PMID 32973810, 2020). "To further determine the role of AdipoR1 in the pathogenesis of autoimmune arthritis, we observed the incidence of arthritis in T cell-specific AdipoR1 KO AIA mice." (PMID 32973810, 2020).
asthma (2 papers, 2020 to 2023). "As increased BMI was linked to increased asthma risk, we investigated how additional weight gain affected lung Tregs and their AdipoR1 expression level during allergic airway inflammation." (PMID 33256137, 2020). "AdipoR1 is expressed in airway epithelial cells in chronic obstructive pulmonary disease; while AdipoR2 is more highly expressed in people with asthma." (PMID 37149591, 2023).
benign prostatic hyperplasia (2 papers, 2012 to 2017). A non-cancerous nodular enlargement of the prostate gland. "Benign prostatic hyperplasia tissues had a decreased expression of AdipoR1 and increased expression of p-p90RSK compared with normal prostate tissues." (PMID 29179455, 2017).
diabetic cardiomyopathy (2 papers, 2014 to 2019). Diabetic cardiomyopathy is a disorder of the heart muscle in people with diabetes. "The HFD-feeding associated downregulation of AdipoR1 detected in heart, kidneys and liver suggests that impaired gene expression of OXPHOS proteins in diabetic complications may, at least in part, be driven by impaired AdipoR1/adiponectin signaling, in particular in diabetic cardiomyopathy." (PMID 31920982, 2019).
dry eye (2 papers, 2022). "As a further support for the presence of AdipoR1/R2 in corneal epithelial cells, topically administered adiponectin proved effective to reduce inflammation of the ocular surface in a mouse model of experimental dry eye and corneal neovascularization in a rabbit." (PMID 36293057, 2022).
gestational diabetes (2 papers, 2019 to 2022). Carbohydrate intolerance first diagnosed during pregnancy. "The genotypes AA and GG of the ADIPOR1 gene rs2275738 polymorphism were connected with an increase in the HOMA–IR index and gestational diabetes in the Russian population." (PMID 35366291, 2022).
Hepatic fibrosis (2 papers, 2022 to 2024). The presence of excessive fibrous connective tissue in the liver. "Adiponectin may also attenuate liver fibrosis by inducing nitric oxide production of hepatic stellate cells that constitutively express both AdipoR1 and AdipoR2." (PMID 35831700, 2022). "Recently, the dual AdipoR1/AdipoR2-based agonist JT003 has been demonstrated to enhance fatty acid oxidation and glucose uptake and mitigate liver fibrosis and insulin resistance in mice via signaling pathways, including AMPK, PPARα, and AKT." (PMID 39737222, 2024). "A study demonstrated that AdipoR1 knockout in mice had no significant impact on hepatic fibrosis progression, whereas AdipoR2 knockout exhibited a marked increase in hepatic fibrosis, highlighting the critical role of AdipoR2 in fibrosis development." (PMID 39737222, 2024).
hypoadiponectinemia (2 papers, 2014 to 2024). "Previous studies from our laboratory on ccRCC patients and ccRCC models in vitro and in vivo have shown that adiponectin has tumor-suppressive effects and that this hormonal axis is inhibited in ccRCC secondary to hypoadiponectinemia and underexpression of AdipoR1 in the tumor tissue." (PMID 24594673, 2014).
ischemia (2 papers, 2019 to 2020). A hypoperfusion of the BLOOD through an organ or tissue caused by a PATHOLOGIC CONSTRICTION or obstruction of its BLOOD VESSELS, or an absence of BLOOD CIRCULATION. "This might be an endogenous protection against ischemic injury and implicated an important role of AdipoR1 in ischemia." (PMID 31231213, 2019). "Interestingly, the expression of AdipoR1 increased dramatically in the cortex and striatum, regions that are highly vulnerable to ischemia." (PMID 31231213, 2019). "We also found that AdipoR1 level increased in cortex and striatum, a region that is vulnerable in ischemia, suggesting it might be an endogenous protective mechanism through AdipoR1." (PMID 31231213, 2019).
keloid (2 papers, 2017 to 2020). An irregularly shaped, elevated mark on the skin caused by deposits of excessive amounts of collagen during wound healing. "Thus, adipoR1 is involved in adiponectin-mediated signalling pathways in KFs, and the adiponectin/adipoR1 interaction may play an important role in the development of keloids." (PMID 28498357, 2017). "Adiponectin Receptor 1 (AdipoR1) has been shown to substantially contribute to the ADP355-induced antifibrotic effect, as well as adiponectin recombinant-mediated pathways in keloids." (PMID 32325772, 2020).
lipodystrophy (2 papers, 2014 to 2017). A congenital or acquired disorder characterized by abnormal loss or redistribution of the adipose tissue in the body. "ADP355 and related peptides with AdipoR1/2 receptor agonist activity show efficacy in models of cancer, lipodystrophy and brain inflammation." (PMID 28667272, 2017).
liver diseases (2 papers, 2013 to 2019). "AdipoR1 is abundantly expressed in heart and skeletal muscle, whereas AdipoR2 is supposed to be the main receptor in the liver, suggesting an association with the pathology of liver diseases." (PMID 30894877, 2019).
lung carcinoma (2 papers, 2015 to 2020). "Immunohistochemical staining and western blotting of lung cancer tissue showed an increased expression of adiponectin and adiponectin receptor 1 in the lung cancer tissue than in normal lung tissue." (PMID 26656720, 2015). "Indeed, AdipoR1 expression was significantly higher in lung cancer specimens than normal healthy lung tissues." (PMID 32570854, 2020). "The expression of adiponectin receptor 1 is a favorable prognostic factor for lung cancer." (PMID 26656720, 2015).